HIF1A (hypoxia inducible factor 1 subunit alpha)
Diseases named in the same sentence as HIF1A in open-access papers (continued):
Sharing a sentence is not in itself a finding about the gene and the disease.
tumor (continued). "Moreover, HIF-1α orchestrates also pH stability of the tumor cells and extracellular matrix adaption, which is linked to alterations of the metabolic program by affecting the expression of the HIF-regulated pathway components." (PMID 27044404, 2016). "Consistently, both mechanosignalling and TNC were elevated in constitutively active HIF1α tumours." (PMID 27820599, 2016). "However, we selected A549 cells for further study, because it is well known that A549 cells expressing higher levels of more stable HIF-1α, which is important for tumor cells with limited oxygen supplies and it, is involved in proliferation and angiogenesis." (PMID 26867977, 2016). "HIF-1α regulates various genes to enhance tumour progression, angiogenesis, and metastasis." (PMID 27581969, 2016). "Although hypoxia is a key regulator of tumour invasion by activating the transcriptional regulators hypoxia-inducible factors, HIF-1α and HIF-2α (refs 16, 17), the molecular machinery behind evasive resistance in solid tumours following anti-angiogenic therapy is insufficiently understood." (PMID 27470974, 2016). "Our findings show that the anti-tumoral effect of exosomes was associated with a reduction in the tumor hemoglobin content, lower vascular density and loss of VEGF and HIF-1α tissue expression, which probably is a consequence of the lower ROS production induced by MenSC-derived exosomes." (PMID 27286448, 2016). "Elevated HIF-1α levels in rapidly growing cells, like embryo and tumours, not only stimulates glycolysis but restricts mitochondrial respiration through the inhibition of the mitochondrial pyruvate dehydrogenase (PDH), reducing pyruvate flux into the tricarboxylic acid (TCA) cycle." (PMID 26099350, 2016). "Our findings uncover a novel mechanism by which HIF-1α regulates tumor progression and invasion." (PMID 26057751, 2015). "Studies found that HIF-1α is overexpressed in most of human tumor cells." (PMID 25816356, 2015). "On the whole, front of a tumor may expand although at a different rate due to various level of energy obtained from OxPhos activity or HIF-1α-dependent anaerobic glycolysis." (PMID 25897425, 2015). "Moreover, OCT4B enhanced angiogenesis by the upregulation of CD34, VEGF, HIF-1α and IL-6, and promoted tumor cell mobility to the surrounding tissue by the upregulation of MMP2 and MMP9, and the induction of epithelial-mesenchymal transition (EMT)." (PMID 25816351, 2015). "As HIF1α stimulates the expression of glycolytic enzymes and decreases reliance on mitochondrial oxidative phosphorylation in tumor cells, we speculated that OA may regulate glycolysis via SIRT3 through a process involving HIF1α." (PMID 25855962, 2015). "Additionally, our metabolomics analyses further demonstrate that HIF1α mediates altered tumor metabolism in TRACK kidneys, which is highly similar to the changes observed in human ccRCC." (PMID 25830305, 2015). "Furthermore, Torin2 treatment in vivo was associated with reduced phospho-4E-BP1, HIF-1α and survivin protein expression in ATC responsive tumor samples." (PMID 25945839, 2015). "We speculated that HIF1A and EPAS1 overexpression in patients with high-risk NBL will contribute to differentiation therapy resistance and to tumor cell aggressiveness." (PMID 26057707, 2015). "Our data suggest that in the absence of REST, as it occurs in REST-less tumours, there is no repression of HIF1A transcription, therefore positive regulators like NFκB are able to freely drive HIF1A transcription, leading to increased HIF-1α protein expression in hypoxic tumour microenvironments." (PMID 26647819, 2015). "Tumor cells increase the expression of HIF-1α by activating AKT under normoxia." (PMID 25799412, 2015). "Finally, when the HIF-1α expression was inhibited by digoxin, the tumor volume and the SCF level decreased, thereby proving the relationship between HIF-1α and SCF in vivo." (PMID 25799412, 2015).
tumor (continued). "Indeed, we observe that the tumour cell line HepG2, which displays HIF1A mRNA induction in hypoxia, has lower REST level than HEK293." (PMID 26647819, 2015). "Although the initial and effective mechanism for increased activity of HIF-1α is by stabilization of the protein, there have been reports of HIF-1α mRNA being increased in cells in response to hypoxia as well as other stresses, eg. tumor inflammation, invasiveness, metastasis, etc.." (PMID 25734817, 2015). "Numerous studies have investigated the selective application of new treatment modalities based on targeting tumor hypoxia, reporting that hypoxic markers, including HIF-1α, CA9 and VEGF, may be specific and favorable therapeutic targets." (PMID 25789026, 2015). "Previous studies indicate that cancer cells appear to display overexpression of this metabolic hypoxia-related protein in most tumor cases, and a high HIF-1α level is related to an enhanced grade of tumor aggressiveness, higher incidences of metastasis, and poor prognosis." (PMID 25412955, 2015). "Increasing evidence supports the hypothesis that the PI3K/Akt/mTOR pathway acts as a master switch controlling HIF-1α synthesis, thereby determining whether cells, especially tumor cells, grow and proliferate." (PMID 26047481, 2015). "Targeting HIF-1 for cancer therapy was based originally on the critical roles of HIF-1α in cancer biology, the association of HIF-1α overexpression with increased patient mortality in various cancer types, and the marked effects on tumor growth by inhibiting HIF-1α activity in preclinical studies." (PMID 25893706, 2015). "In addition, curcumin has been found to inhibit VEGF production from various tumor cells though down-regulation of HIF1-α expression." (PMID 26254223, 2015). "Moreover, because the level of miR-210 is dependent on the level of HIF-1α, the presence of elevated miR-210 in tissues has become a predictive marker for tumor hypoxia." (PMID 25809609, 2015). "MT1-MMP controls a variety of signaling pathways and cell functions, including necrosis/apoptosis, NF-κB-mediated cyclooxygenase-2 (COX-2) expression, hypoxia-inducible factor-1 alpha (HIF-1α)-mediated response of tumor cells to hypoxia, and vascular smooth muscle cell differentiation." (PMID 26331622, 2015). "Hypoxia-inducible factor 1α (HIF-1α) plays an important role in tumor growth and metastasis." (PMID 26115041, 2015). "Tumours contain hypoxic regions, with increased HIF-1α protein levels." (PMID 25695215, 2015). "In addition to its known function as a tumor suppressor, Foxo3a has been shown to inhibit HIF-1α transcriptional activity by competing for p300 binding during vascular development, and to suppress EMT, in part, through the regulation of E-cadherin expression." (PMID 25821081, 2015). "Moreover, reduced activity of mitochondrial complex II (succinate-ubiquinone oxidoreductase, Sdh) due to diminished activity of the B subunit (ShdB) in such cells, favors tumor cell growth in a HIF1α-dependent manner." (PMID 26584646, 2015). "EGFR is involved in the tumor angiogenesis of HNSCC via the HIF-1α and Notch1 pathways." (PMID 25723392, 2015). "Furthermore, a recent clinical study comparing the effect of neoadjuvant letrozole with that of letrozole plus metronomic cyclophosphamide on tumor growth inhibition revealed that increased HIF-1α expression significantly predictive of therapeutic resistance." (PMID 25929338, 2015). "SB202190 induced sensitization of tumor cells to 2-DG and D-allose may be partially mediated by inhibition of HIF-1α activity." (PMID 25888489, 2015). "It is well known that in addition to the Warburg effect, expression of PKM2 and LDHA in tumour tissues may be regulated by Hypoxia inducible factor 1-alpha (HIF1a) and c-Myc." (PMID 25880801, 2015). "Thus, the ability of ILK to downregulate Foxo3a expression, in conjunction with HIF-1α overexpression, plays a critical role in facilitating hypoxia-mediated tumor progression and metastasis." (PMID 25821081, 2015).
tumor (continued). "The fact that a large fraction of HNSCC tumor cells exhibiting high HIF1α expression could be one of the reasons for this." (PMID 25714028, 2015). "And its activity in reducing HIF-1α in tumor cells was more potent than in endothelial cells." (PMID 26202747, 2015). "Finally, the anti-tumor effect of HIF-1α knockdown (KD) plus GI was evaluated using a tumor xenograft model, where a hypoxic environment naturally exists." (PMID 26339797, 2015). "By regulating the transcription of angiogenic factors, including VEGF, basic fibroblast growth factor and matrix metalloproteinase-9, HIF-1α could promote tumor-derived angiogenesis." (PMID 25997612, 2015). "Given the ability of HIF-1α protein to degrade Foxp3 (refs 32, 33), we propose that DTX1 may also contribute to the stability of tumour-infiltrated Tregs by antagonizing HIF-1α." (PMID 25695215, 2015). "In conclusion, the expression of hypoxic markers, including HIF-1α, CA9, GLUT1 and VEGF is common in patients with STS and is strongly associated with tumor progression, as indicated by the significant association of their expression with higher histological grade and advanced tumor stage." (PMID 25789026, 2015). "Indeed, tumor lesions from the HIF1α(PP) cells were numerous foci throughout the brain; in addition to the cerebral cortex, invasions were identified in the hypothalamus, midbrain, hindbrain, and even cerebellum." (PMID 25893706, 2015). "Increased HIF1α abundance promotes tumor growth and angiogenesis." (PMID 25622105, 2015). "HIF-1α expression is also central to tumor progression and neo-angiogenesis." (PMID 26343197, 2015). "Furthermore, in the Versteeg dataset, high mRNA levels of HIF1A and EPAS1 were still significantly associated with lower overall survival and relapse-free survival in the sub-set of patients with advanced-stage tumor (i.e., stage 4)." (PMID 26057707, 2015). "To test whether transient induction of HIF1α(PP) would produce similar effects in vivo, we analyzed tumor growth of U-87 MG cells that had been treated with tetracycline in culture for only 2 days before intracranial transplantation." (PMID 25893706, 2015). "The analysis of the xenografts demonstrated a notable correlation between HIF-1α expression levels and tumor sizes, confirming that HIF-1α could promote xenograft growth." (PMID 25811359, 2015). "Furthermore, we validated the effect of HBXIP on PDHA1, SCO2 or HIF1α in xenograft tumor tissues by Western blot analysis and IHC analysis, respectively." (PMID 26309161, 2015). "Indeed, HIF-1α has been demonstrated to be important for HER2 signaling-induced tumor progression and angiogenesis." (PMID 26625311, 2015). "Histological examination at high magnification revealed aggressive invasion of round cells in the HIF1α(PP)-derived tumors, whereas relatively low-density, spindle-shaped tumor cells were frequently observed interwoven with fibrous tissues in β-gal and HIF2α(PP) tumors." (PMID 25893706, 2015). "HIF-1α immunoreactivity was observed in 88.4% (84/95) of tumor samples examined." (PMID 26312763, 2015). "Due to the already mentioned importance of hypoxia with subsequent activation of HIF‐1α and the implication in tumour metabolism, plus the observation that MCT4 mRNA and protein levels clearly increase in hypoxic conditions, we assessed the effects of MCTs knockdown under hypoxic conditions." (PMID 25875424, 2015). "During epithelial invasion of the mammary fat pad, oxygen homeostasis is challenged in a similar way to the invasive front of tumours, and HIF-1α levels may increase in response to local hypoxia." (PMID 25955753, 2015). "It has been reported that HMM cells silenced for ERK1/2 are more sensitive to doxorubicin and have a lower expression of Pgp: our results provide an explanatory mechanism for this observation, showing that Pgp transcription is sustained by the Ras/ERK1/2/HIF-1α axis in this tumor." (PMID 25544757, 2015).
tumor (continued). "Similarly, both cell scratch and transwell chambers results showed that the decreased tumor cell invasion rate following HIF-1α knockdown can be rescued by adding exogenous SCF (p<0.05)." (PMID 25799412, 2015). "In this study, overexpression of GSK-3β dramatically down regulates HIF-1α protein expression as well as VEGF mRNA levels, Thus, HIF-1α/VEGF pathway may be involved in transmitting the biological effects of GSK-3β- inhibited tumor growth and angiogenesis." (PMID 26388612, 2015). "Hypoxia may also have a significant influence on macrophage/DC function, in addition to promoting cancer cell stemness and tumor survival through HIF-1α/Notch-1 signaling." (PMID 26343197, 2015). "Therefore, the pivotal roles of VEGFR2 and HIF1α in tumor angiogenesis, as widely documented in the literature and observed in our study, appear to be more pronounced at the time of initial diagnosis compared with at recurrence." (PMID 25860928, 2015). "The results of the present study suggest that targeting EGFR may suppress HIF-1α-mediated tumor angiogenesis." (PMID 25997612, 2015). "Since HIF2α, like HIF1α, also affects tumor progression and tumor stem cell function, IRP-1 could also play a role in tumorigenesis." (PMID 25970586, 2015). "Furthermore, SCF promoted PDAC cell proliferation and invasion, and the decreased tumor cell proliferation and invasion abilities following HIF-1α knockdown can be rescued by the up-regulation of SCF under hypoxia." (PMID 25799412, 2015). "For tumor this change could be disadvantageous, since cells in hypoxia would fail to accumulate enough HIF-1α in order to trigger adequate pro-angiogenic adaptations." (PMID 26588727, 2015). "A previous biological analysis in the tumor tissue from a PGL patient harboring a loss-of-function SDHD germline mutation (R22X) showed that SDH activity was abolished due to the mutation and associated with increased expression of HIF-1α." (PMID 25149476, 2015). "In pVHL −/− ccRCC, in contrast, HIF-1α appears to act as a tumor-suppressor." (PMID 26210994, 2015). "As the key transcription factor of glycolytic process, many tumor suppressors with emerging role in regulation of aerobic glycolysis may control glycolytic genes' expression through HIF-1α regulation." (PMID 25685782, 2015). "Numerous reports demonstrated that inhibition of HIF-1α could overcome resistance of tumor cells to chemotherapy." (PMID 25544770, 2015). "Furthermore, in hypoxic environments, melatonin is able to decrease HIF-1α expression levels in several tumor types." (PMID 26252771, 2015). "Similarly, overexpression of certain miRs can encourage tumor growth and cancer by downregulating endogenous tumor suppressors such as miR-199a and miR-20b, the latter of which downregulates HIF-1α during hypoxia by targeting its 3' UTR." (PMID 25809609, 2015). "Treatment with ITZ also decreased tumour vascular area but increased expression of HIF1α." (PMID 25932045, 2015). "Therefore, SA is a leading candidate for the development of anticancer agents, and these mechanisms will be a key therapeutic target for pharmacologic and therapeutic intervention in HIF-1α-driven tumor growth and cell death." (PMID 26610526, 2015). "We also demonstrated that HIF-1α expression in xenografts was associated with increased vascularization, which might be involved in the HIF-1α-promoting NB tumor progression." (PMID 25811359, 2015). "Tumor incidence of the HIF1α(PP) cells was 5/6, similar to that of the control (4/6)." (PMID 25893706, 2015). "In this study, we analyzed genotypes of VEGF-A, KDR, Flt4, PDGFRα, HIF-1α and ERCC1 in TETs, aiming to verify whether they correlate with increased tumor risk and/or with the outcome of these patients." (PMID 26254278, 2015). "This increase in CSCs generated by tumour hypoxia was mediated by HIF-1α and may limit the efficacy of antiangiogenic agents." (PMID 25612916, 2015). "Studies have shown that HIF-1α can regulate the invasion of tumor cells." (PMID 25816356, 2015).
tumor (continued). "Moreover, ILK has been demonstrated to play important roles in tumor angiogenesis and radioresistance by upregulating HIF-1α-dependent expression of vascular endothelial growth factor (VEGF) and survivin, respectively." (PMID 25821081, 2015). "To explore whether the combination of endogenous succinate accumulation and hypoxia was sufficient to drive dioxygenase inhibition in these PGL tumor specimens, we evaluated levels of HIF1α, HIF2α, histone methylation, and cytosine methylation." (PMID 25985299, 2015). "In vivo, OA also suppresses tumor growth through destabilizing HIF1α and upregulating SIRT3." (PMID 25855962, 2015). "Also the impaired oxygenation in tumor spheroids leads to up-regulation of Hif1α and subsequently to increased expression of ABC transporters like MDR143." (PMID 26620400, 2015). "HIF-1α was readily detectable in tumour sections by immunofluoresence." (PMID 25612916, 2015). "As a consequence, HIF-1a is destabilized, being tumor growth arrested." (PMID 26462158, 2015). "Finally, we analyzed the in vivo effect of HIF-1α knockdown plus GI treatment using a tumor xenograft model." (PMID 26339797, 2015). "STAT3 signaling has also been widely implicated in tumor progression and tumor cell stemness, not least through induction of HIF-1α and Notch1." (PMID 26343197, 2015). "HIF1α is a crucial downstream target of miR-21 in regulating tumor angiogenesis." (PMID 26116372, 2015). "In this tumor, HIF-1α/2α appear to have contrary effects on c-Myc." (PMID 26210994, 2015). "Thus, exposure of tumor cells to metronomic topotecan causes a decreased expression of VEGF, likely as a result of HIF1α downregulation." (PMID 26623560, 2015). "Therefore, in order to evaluate tumor hypoxia, immunostaining for Hif1α was performed in prostatic samples from TRAMP eJag1 mutants." (PMID 26213336, 2015). "Interestingly, HIF1α, an important mediator of tumor angiogenesis, was identified as a key transcription factor with p-value 4.2 × 10−147, as it affected the expression of 115 of the differentially expressed genes." (PMID 25896712, 2015). "Notably, blocking ERK activation with U0126 enhanced FOXO3a-mediated miR-622 transcription that resulted in inhibition of HIF-1α expression in cancer cells, leading to decreased tumor invasion and metastasis." (PMID 26528854, 2015). "Since the discovery that the HIF-1 pathway regulates the activation of many proangiogenic factors in tumours and may promote metastasis, the HIF-1α subunit has been considered an attractive target for new cancer therapeutics." (PMID 26146622, 2015). "Tumor hypoxia and increased HIF-1α activity facilitate the tumor aggressiveness and progression." (PMID 26512660, 2015). "However, as only qualitative data is possible with immunohistochemistry, mRNA levels of HIF-1α were used in this study to determine the quantitative value for degree of hypoxia within a local tumor region." (PMID 25734817, 2015). "Another explanation could be that HIF-1α is regulated by other factors than tumour hypoxia, such as oncogenic signalling or growth factors." (PMID 26501874, 2015). "Therefore, inhibiting tumor angiogenesis via suppression of HIF-1α/VEGF-A signaling represents a promising strategy for anticancer treatment." (PMID 25649293, 2015). "Previously, we reported the usage of anti-hTfR scFv fused viral peptide/HLA-A2 complex to redirect cytotoxic T cells of viral specificity to TfR-expressing K562 cells and Tf conjugated polyplexes to deliver therapeutic HIF-1α shRNA into various TfR-expressing tumor cell lines." (PMID 25803700, 2015). "However, the influence of UCHL1 on HIF-1α expression observed in the present study appeared to be greater in clinical tumour tissues than in cancer cells cultured under simple low-oxygen conditions." (PMID 25615526, 2015). "Interestingly, HIF-1α expression was significantly increased in the inner portions of tumour sections compared with the tumour periphery." (PMID 25612916, 2015).